CRP (C-reactive protein)
Diseases named in the same sentence as CRP in open-access papers (continued):
Sharing a sentence is not in itself a finding about the gene and the disease.
lymphopenia (continued). "The patients with severe disease were older and had high ferritin, D-dimer, C-reactive protein, troponin, interleukin-6 (IL-6) levels, and neutrophilia with lymphopenia at admission." (PMID 34440121, 2021). "GDF-15 levels also correlated with interleukin-6, C-reactive protein, ferritin and D-dimer levels and with neutrophilia and lymphopenia." (PMID 34829345, 2021). "Lymphopenia was common, as were elevations in C-reactive protein (CRP) (median 75 mg/L, IQR 28–143) and creatinine (median 92 mg/L, IQR 68–130)." (PMID 33564474, 2021). "Biological evaluation revealed an inflammatory syndrome, with hyperleukocytosis at18730 lymphopenia at 460 cells/μ L, C-reactive protein at 116 mg/L procalcitonin at 0.17 ng/ml, and ferritin at1502, fibrinogen level." (PMID 34178313, 2021). "The cost per patient in patients with neutropenia, lymphopenia, elevated ferritin, CRP > 41.8 mg/L and those patients who died was significantly (p = 0.000) higher than that in patients who did not have these outcomes." (PMID 34623528, 2021). "In confirmation of our findings, a recent meta-analysis revealed that the most frequent laboratory abnormalities were lymphopenia (35–75% of cases), increased CRP levels (75–93% of cases), LDH (27–92% of cases), and ESR (up to 85% of cases)." (PMID 34535175, 2021). "Lymphopenia was detected in 20,7%, thrombocytopenia in 4.2%, elevated values of CRP in 32.6%, LDH in 54.3%, D-Dimer in 26.3% and ferritin in 31.3% of the patients included in the study." (PMID 34803451, 2021). "The interpretation of blood results is an important component of the triaging pathway and identification of key features, raised CRP and lymphopenia, allows for the indication of patients with likely COVID-19 infection." (PMID 32439731, 2021). "Cytokine release syndrome (CRS) manifests many abnormalities such as lymphopenia, high levels of C-reactive protein (CRP), high Ferritin, high D-dimers, high lactate dehydrogenase (LDH) and interleukin-6 (IL-6)." (PMID 33411791, 2021). "Cluster 1 (hyperinflammatory immune response) was characterized by the high CRP levels, neutrophilia, and lymphopenia." (PMID 33850271, 2021). "Lymphopenia, elevated C-reactive protein (CRP), and increased level of white blood cell (WBC) were associated with increased death risk." (PMID 34777862, 2021). "MRI results revealed no acute lesions, and the results of EEG and CSF analysis were normal, but further laboratory investigations showed lymphopenia and elevated CRP." (PMID 33803475, 2021). "Patients with high troponin T levels also presented higher inflammatory biomarkers, such as leukocytosis, lymphopenia, D-dimer, C-reactive protein and pro-calcitonin." (PMID 34359355, 2021). "The LOS was significantly (p = 0.000) longer in the patients who had CRP > 41.8 mg/L (3.8 days), received O2 therapy (3.7 days), had elevated ferritin levels (3.5 days), had lymphopenia (2.6 days) and patients with SpO2 < 94% (2.5 days)." (PMID 34623528, 2021). "The LCR can capture the early part of the inflammatory cascade more sensitively than the NLR as the CRP levels have been shown to rise earlier than either neutrophilia or lymphopenia is seen in the course of disease." (PMID 35368452, 2021). "Laboratory tests were performed revealing leukopenia, lymphopenia, thrombocytopenia, an important inflammatory syndrome (CRP = 235 mg/L), and an elevated brain natriuretic peptide value (BNP) of 344 pg/mL." (PMID 33921718, 2021). "If necessary, patients with increased CRP, lymphopenia and increased LDH should be followed closely and transferred to ICUs." (PMID 34445855, 2021). "Concerning the biological tests, 41 patients (83.7%) had lymphopenia, 35 (71.4%) had hyperleucocytosis, 40 (81.6%) had elevated CRP levels, 28 (57.1%) had elevated serum LDH levels and 19 (38.8%) had cytolysis." (PMID 34185186, 2021). "CT severity score was found to be positively correlated with lymphopenia, increased serum CRP, d-dimer, and ferritin levels (p < 0.0001)." (PMID 33505722, 2021).
lymphopenia (continued). "Chest CT and X- ray imaging results were normal, but laboratory investigations revealed lymphopenia and elevated CRP." (PMID 33803475, 2021). "CRP was elevated in 96.2%, ferritin was >500 mg/dL in 60%, D-dimer was >1 ng/mL in 58.4%, lymphopenia was present in 55.7%, and hyperinflammatory syndrome in 61.6%." (PMID 34664862, 2021). "Fever and mild respiratory symptoms were the most frequently reported symptoms and raised C-reactive protein level, lymphopenia, raised white cell count and raised procalcitonin level were the most frequent laboratory findings." (PMID 34185807, 2021). "Laboratory analyses revealed lymphopenia, neutrophilia, high C-reactive protein (CRP) levels and elevated lactate dehydrogenase (LDH) levels." (PMID 34088268, 2021). "Abnormal findings in the two studied groups were leukopenia, lymphopenia, high CRP and ferritin levels." (PMID 33765980, 2021). "Cytokine storms can manifest as lymphopenia and elevated serum markers of inflammation including D-dimer, IL-6, ferritin and C-reactive protein (CRP) that can lead to multi organ failure." (PMID 34457265, 2021). "Tocilizumab relieves clinical symptoms, reduces the requirement for supplementary oxygen, reverses lymphopenia and decreases C-Reactive Protein (CRP) levels." (PMID 34150793, 2021). "At admission, lymphocytopenia was present in 86% of patients; increased D-dimer and CRP levels were found in 84.2% and 87.7% of patients respectively, while PCT values > 0.5 μg/L were observed in 47.4% of patients." (PMID 33556140, 2021). "The correlation between the high level of CRP and the severity of COVID-19 disease has been well established in the literature, as is the combination of lymphopenia and CRP concentration as a sign of severe infection." (PMID 33467466, 2021). "Biological (lymphopenia, hyperferritinemia, serum C-reactive protein [CRP] levels) predictors have been reported but remain mostly undescribed in the North African region." (PMID 33539383, 2021). "They had the lowest hemoglobin results (11.8 vs. 13 g/dL; p = 0.01), the highest lymphopenia results (650 vs. 940/mm3; p = 0.01), and the highest CRP (31.9 vs. 24 mg/dL; p < 0.02) values." (PMID 34150790, 2021). "At admission lymphopenia, a mild increased level of C-reactive protein and normal prothrombin and activated partial thromboplastin times were seen." (PMID 33540596, 2021). "Significant predictive factors associated with hospitalization, after adjusting for age and sex, were lymphopenia (OR = 3.48; 95%CI = 1.67 to 7.40) and elevated C-reactive protein (OR = 3.27; 95%CI = 1.59 to 7.18)." (PMID 32822413, 2020). "Most patients with COVID-19 pneumonia would develop new pulmonary lesions during treatment, especially those with lymphopenia, elevated CRP, or primary lesion progression." (PMID 32922203, 2020). "Measures of inflammation – C-reactive protein and IL-6 – normalized quickly in most patients, as did lymphopenia, in correlation with improved oxygenation." (PMID 32503877, 2020). "Hyponatremia, lymphopenia, elevated C-reactive protein, and ferritin were observed in complementary tests." (PMID 32682452, 2020). "Laboratory parameters detected within sufferers in our study population were lymphocytopenia, leukopenia, thrombocytopenia, deranged liver function enzyme levels, elevated CRP, and D-dimers coinciding with results of numerous studies." (PMID 32699707, 2020). "Laboratory markers include lymphopenia, elevated C-reactive protein, and elevated levels of proinflammatory cytokines." (PMID 32735546, 2020). "Evaluation of inflammatory markers revealed a statistically significant association between lymphopenia, elevated LDH, and CRP with severe disease." (PMID 33042695, 2020). "In our cases, the infant presented neutropenia, while the teenager patient was found with lymphopenia, both being encountered with a leucocyte count within the normal ranges and normal CRP level." (PMID 33194909, 2020).
lymphopenia (continued). "Laboratory data revealed lymphopenia (510 cells/μL) and elevated serum CRP (9.93 mg/dL) and ferritin (269 ng/mL) levels." (PMID 32871900, 2020). "At the seventh day his clinical condition had improved, with no fever, no dyspnea, no thrombocytopenia, with normal arterial-blood gases and improvement of the C-reactive protein levels, but remaining with leukopenia and lymphopenia." (PMID 32331519, 2020). "Fever (88.7%), cough (64.2%), fatigue (34%), and abnormal laboratory indicators, including lymphopenia, reduced albumin, albumin/globulin (A/G), and elevated C-reactive protein (CRP), were mainly observed." (PMID 32746805, 2020). "CRP level higher than 75 mg/L and lymphopenia below 800/mm3 increased by two fold the odds of being transfer in ICU or death." (PMID 33075088, 2020). "In the univariate logistic regression analysis, we found that higher odds of ICU admission were related to older age, respiratory rate over 24 breaths per min, lymphopenia, and increased levels of CRP, TnI, brain natriuretic peptide, and creatinine." (PMID 32765943, 2020). "For the prediction of bilateral lung involvement, the AUC of lymphopenia was 0.714 compared to 0.782 and 0.672 for CRP and LDH, respectively." (PMID 33206680, 2020). "Typical laboratory findings were lymphopenia, high C-reactive protein, and lactate dehydrogenase plasma levels." (PMID 33490013, 2020). "For the prediction of abnormal lung images on discharge, the AUC of lymphopenia was 0.792 compared to 0.856 and 0.782 for CRP and LDH, respectively." (PMID 33206680, 2020). "Our data has once again provided evidence for the role of CRP and lymphopenia, among other markers in the stratification of the disease’s severity and prognosis." (PMID 32668763, 2020). "Information from research centre tests indicated that five of the nine parturients with COVID-19 pneumonia had lymphopenia. patients had raised C- reactive protein (>10 mg/L) relevant to our evaluation with the mean value of (8.50±.96)." (PMID 33235588, 2020). "Lymphopenia (1/3), thrombocytopenia (1/3), raised lactate dehydrogenase (1/3), D-dimers (2/3), fibrinogen (2/3), and C-reactive protein (CRP; 2/3) were identified, but hypoxemia and radiographic signs of COVID-19 pneumonia were absent." (PMID 33102507, 2020). "Lymphopenia and elevated levels of neutrophil count, C-reactive protein, interleukin 6, D-dimer, creatinine, lactate dehydrogenase, cTnT, and NT-proBNP were more commonly seen in severe cases." (PMID 33092539, 2020). "Administration of tocilizumab resulted in a reduction in blood proinflammatory markers such as CRP, improved chest CT findings, restoration of lymphopenia, and improved oxygen support." (PMID 32595947, 2020). "The main laboratory parameters were lymphopenia (33%), elevated D-dimer (52%), and C-reactive protein (40%)." (PMID 33574819, 2020). "Severe disease and death are associated with high levels of inflammatory parameters represented by elevated C-reactive protein, neutrophilia and lymphopenia." (PMID 33272355, 2020). "The laboratory values on admission were consistent with an impaired immune-inflammatory profile, characterized by lymphopenia and elevated D-dimer, procalcitonin, ferritin and C-reactive protein levels." (PMID 32512688, 2020). "In COVID-19, prognostic factors of severe disease course include elevated CRP, IL-6, ferritin and D-dimer, lymphopenia, decreased monocyte and T cell counts." (PMID 33574819, 2020). "With regard to laboratory data, the presence of lymphopenia (p = 0.005), high level of CRP (p < 0.0001), LDH (p < 0.0001), hepatic enzymes (p = 0.0009) or CK (p = 0.02), PaCO2 (p = 0.02) and a reduction in blood’s pH (p = 0.04) were more common in CRX+." (PMID 32894449, 2020). "The most common laboratory abnormalities were: lymphopenia, increased levels of C-reactive protein (CRP) and D-dimer." (PMID 33317458, 2020).
lymphopenia (continued). "Among the laboratory abnormalities, elevated C-Reactive Protein (CRP) (72.0%, CI 54.3-84.6) and lymphopenia (50.1%, CI 38.0-62.4) were the most common." (PMID 32793620, 2020). "Lymphopenia was also correlated with severity grades of pneumonia (P<0.001) and C-reactive protein (CRP) level (P = 0.0014)." (PMID 33206680, 2020). "Cirrhotic mice had the typical abnormalities of leucopenia, lymphopenia, thrombocytopenia, hypoalbuminemia, abnormal liver function, high serum C-reactive protein (CRP), and high lipopolysaccharide binding protein (LBP) levels." (PMID 32138352, 2020). "In this cohort, lymphopenia and elevation of CRP and lactate dehydrogenase levels were more severe in patients who received corticosteroids therapy." (PMID 33172477, 2020). "Lymphopenia (64.5%), increased C-reactive protein (44.3%), increased lactate dehydrogenase (28.3%), and leukopenia (29.4%) were also recorded." (PMID 33206816, 2020). "For the prediction of severe or critical disease, the area under the curve (AUC) of lymphopenia was 0.854 compared to 0.870 for CRP and 0.810 for LDH." (PMID 33206680, 2020). "We found that patients had increased inflammatory markers including elevated CRP in 50%, lymphopenia in 36% and elevated ESR in 25% which is similar to other respiratory infections (SARS, influenza)." (PMID 33110589, 2020). "In two of the six cases, a detailed laboratory investigation revealed lymphopenia and elevated C-reactive protein." (PMID 32566429, 2020). "The most common abnormal laboratory changes were lymphopenia, high concentrations of C-reactive protein, and elevated levels of aspartate aminotransferase; however, we do not know the exact pathogenesis and the reason for these alterations." (PMID 32574328, 2020). "The most common laboratory findings include lymphopenia, elevated C-reactive Protein (CRP), elevated aspartate aminotransferase, hypoalbuminemia, elevated procalcitonin level, elevated D-dimer and erythrocyte sedimentation rate (ESR)." (PMID 33282890, 2020). "Examining laboratory indicators of patients also revealed an increase in white blood cells, thrombocytopenia, lymphopenia, C-reactive protein, and alanine aminotransferase (U / L)." (PMID 33169720, 2020). "Blood tests showed mild lymphopenia (900/mmc) and high C-reactive protein (CRP) levels (56 mg/L, normal value <5); therefore, an ongoing infective process was suspected." (PMID 32550070, 2020). "In a systematic review and meta-analysis of 43 studies involving 3,600 patients, the most common laboratory abnormalities included elevated C-reactive protein (68.6%), lymphopenia (57.4%), and elevated lactate dehydrogenase (LDH) (51.6%)." (PMID 32850602, 2020). "The main reported laboratory findings were lymphopenia, elevated C-Reactive Protein (CRP), Amino alanine transferase (ALT), and Aspartate amino transferase (AST)." (PMID 32440660, 2020). "Lymphopenia and elevated CRP and CK levels peaked in the second week after symptom onset, thus possibly indicating disease progression." (PMID 32226287, 2020). "Laboratory findings showed that the most common abnormalities were lymphopenia (75 (78.9%)), elevated D-dimer (60 (63.2%)), and elevated C-reactive protein (56 (58.9%)) on admission." (PMID 33062082, 2020). "Laboratory findings such as lymphopenia (N=19), elevated C-reactive protein (N=29); alanine aminotransferase (ALT) and aspartate aminotransferase (AST) (N=3) and decreased Albumin (N=1) were reported in most studies." (PMID 32440660, 2020). "Regarding the laboratory data in our series, specific biological parameters were predictive of the severity of the clinical outcome of our patients, such as elevation of LDH, ferritin, D-dimers, CRP, neutrophils, and lymphopenia." (PMID 33033687, 2020). "An important finding of our study was the presence of lymphopenia and elevated inflammatory markers including CRP, LDH, Ferritin, D-dimer, and IL-6 levels in almost all patients who developed spontaneous pneumothorax." (PMID 32938445, 2020).
lymphopenia (continued). "Dynamic profile of the three major findings/predictors (i.e. C-reactive protein, lymphopenia and BUN), were tracked from 24 hours at admission, during hospitalization and from the last laboratory findings before discharge or death, respectively." (PMID 32651993, 2020). "We noted significantly elevated liver enzymes (ALT, AST), neutrophilia, lymphopenia, and elevated neutrophil-to-lymphocyte ratio, CRP, and ferritin levels among our cohort." (PMID 33457138, 2020). "Laboratory findings were described in a lower number of patients and revealed lymphopenia (0.93 × 109/L, 95% CI 0.83–1.03 × 109/L, n = 464) and abnormal C-reactive protein (33.72 mg/dL, 95% CI 21.54–45.91 mg/dL; n = 1637)." (PMID 32235486, 2020). "A systematic review on children with MIS-C reported neutrophilia in 83% of cases, raised CRP in 94%, lymphopenia in 50%, raised Troponin-T in 68% and raised proBNP in 77% of cases." (PMID 33859967, 2020). "The laboratory tests conducted in the Korea National Medical Center for isolation and treatment showed mild lymphopenia in 1267 cells/mm3 (18.1% among white blood cells) and C-reactive protein (CRP) was 8.93 mg/dL (<0.5)." (PMID 32824985, 2020). "Laboratory findings were reported for 108 women out of 275 (39%) and revealed elevated C-reactive protein (CRP) in 52 cases (48%), lymphopenia in 31 cases (29%), and elevated liver enzymes in 9 cases (8%)." (PMID 32570959, 2020). "The disease affects both lungs and most patients exhibit lymphopenia, increased levels of C-reactive protein (CRP), and elevated erythrocyte sedimentation rate (ESR)." (PMID 32923472, 2020). "This study revealed that the risk factors for the death in these elderly patients included comorbidities, increased levels of C-reactive protein and blood urea nitrogen, and lymphopenia during hospitalization." (PMID 32651993, 2020). "Laboratory examination of blood samples taken from 39 patients showed that lymphocytopenia, increased CRP and LDH were the most common results, respectively." (PMID 33224961, 2020). "Laboratory findings commonly reported in COVID-19 include leukopenia and lymphopenia, and elevations in aminotransferase levels, C-reactive protein, D-dimer, ferritin, and lactate dehydrogenase (Lovato A, 2020)." (PMID 33392263, 2020). "To investigate the predictive value of all three variables combined, we further created a scoring system by assigning 1 point for lymphopenia, elevated CRP level and elevated LDH level." (PMID 33206680, 2020). "Laboratory data usually show lymphopenia, decreased albumin, high values of C-reactive protein (CRP), erythrocyte sedimentation rate (ESR), and lactate dehydrogenase." (PMID 32321540, 2020). "A very recent study has reported that elevated CRP and lymphocytopenia were significantly related to the development of ARDS in COVID-19 infection." (PMID 33102532, 2020). "Serum levels of CRP remained high (7.32 mg/dL), and lymphopenia (328/μL) and serum ferritin level (414 ng/mL) worsened." (PMID 32871900, 2020). "On admission, the majority of the cases with laboratory test results had normal or low leukocyte count (146/182; 80.2%), while just under half had lymphocytopenia (85/197; 43.1%) and increased C‐reactive protein (CRP) (90/197; 45.7%)." (PMID 32430957, 2020). "B- complete blood count should be tested to find out leukopenia, lymphopenia, and C-reactive protein is also tested in case of an increase." (PMID 32304191, 2020). "The most commonly reported abnormal laboratory parameters in children were leukopenia/lymphopenia (16–33%), leukocytosis (13%), increased creatine kinase (5–37%), elevated D-dimer (12–52%), CRP (17–40%), AST (19%) and alanine aminotransferase (15%)." (PMID 33859967, 2020). "Lymphopenia, elevated serum markers (C-reactive protein, procalcitonin, IL-6, D-dimer), and chest-X-ray findings consistent with pneumonia are linked to worse prognosis." (PMID 32550702, 2020).